CTHRC1 (collagen triple helix repeat containing 1)
Diseases named in the same sentence as CTHRC1 in open-access papers (continued):
Sharing a sentence is not in itself a finding about the gene and the disease.
cancer (continued). "The components form a CTHRC1-Wnt-Fzd/ROR2 complex to activate the Wnt/PCP pathway selectively and transmit signals from the cell-surface complex to the nucleus by Dvl-RhoA/Rac1-JNK-ATF2/c-Jun cascade, promoting cancer cell protrusions, proliferation, migration, and invasion." (PMID 32848510, 2020). "Therefore, inhibiting CTHRC1-mediated TGF-β signaling pathways may effectively suppress the invasion and angiogenesis of cancer cells." (PMID 32848510, 2020). "The expression of CTHRC1 and the positive correlation between Wnt5a/Ror2 and pathological grade suggests that the Wnt5a/PCP signaling pathway could play a role in the aggressiveness of this cancer." (PMID 28427201, 2017). "Moreover, IHC staining revealed that the cytoplasm of most cells in the carcinoma tissue, but not in the para-carcinoma tissue, were positively stained with CTHRC1." (PMID 29234238, 2017). "It is still not clear how CTHRC1 regulates cancer cell migration." (PMID 23922981, 2013). "However, the functional role of CTHRC1 in HCC and other cancers is still uncharacterized." (PMID 23922981, 2013). "CTHRC1 secreted by osteoclasts promotes basic fibroblast growth factor (bFGF) expression in osteoblasts by stimulating Wnt/β-catenin signaling, which may induce the development of cancerous bone lesions but not mediate vascular production." (PMID 32848510, 2020). "However, whether CTHRC1 is involved in cancer cell invasion and metastasis has not been completely clarified." (PMID 29631554, 2018). "We confirmed expression of two additional upregulated gene candidates, POSTN and CTHRC1, that have not been previously assessed in human MPNST but are known contributors to progression in other human cancer types." (PMID 39511408, 2025). "Unlike CTHRC1, LRRC15 is a cell surface marker, and an antibody drug conjugate against LRRC15 is currently under clinical development to target cancer stromal cells." (PMID 37311583, 2023). "CTHRC1 expression was found to be significantly increased in COAD, regardless of clinical cancer stage, age, sex or race." (PMID 35300110, 2022). "Moreover, analysis of other drugs showed that the IC50 values of PI-103, Hypothemycin, and OSI-027 were also positively correlated with CTHRC1 expression in human cancers, while IC50 values of AFP464 and Aminoflavone showed negative correlations with CTHRC1 expression in human cancers." (PMID 39052013, 2024).
adenocarcinoma (6 papers, 2014 to 2024). A common cancer characterized by the presence of malignant glandular cells. "We identified significant overlap in the SqCC and adenocarcinoma risk signatures for matrix components that regulate collagen fibril architecture including COL10A1, COL11A1, and CTHRC1 suggesting that our risk signature represents changes in the organization of fibrillar collagens." (PMID 36404344, 2022).
infection (4 papers, 2017 to 2025). The state of being infected such as from the introduction of a foreign agent such as serum, vaccine, antigenic substance or organism. "To further explore the molecular mechanisms through which CTHRC1 exerts its effects in CAFs, we constructed stable shRNA knockdown cell lines in CAFs using lentiviral infection to knock down CTHRC1, and the knockdown efficiency was confirmed by Western Blot." (PMID 40751418, 2025). "In this study, we found that the expression of CTHRC1 gradually elevated with the extensive infection of ALV-J tested by the IHC assay." (PMID 33102569, 2020). "Forty-eight hours after infection, overexpression of CTHRC1 in HLK-3 cells was confirmed." (PMID 29285247, 2017).
benign tumor (1 paper, 2015). "We found that CTHRC1 expression was up-regulated in the paraffin-embedded EOC tissues compared to borderline or benign tumor tissues." (PMID 26452130, 2015).
kidney disease (1 paper, 2023). "Based on the studies showing the crucial role of TGFβ in the canonical and non-canonical pathways of kidney disease, we hypothesized that CTHRC1 might have a certain role in CKD’s pathogenesis." (PMID 37109608, 2023).
CTHRC1 also shares sentences with these, for which no sentence is quoted: idiopathic pulmonary fibrosis (7 papers); metastatic melanoma (4); stomach adenocarcinoma (4); esophageal squamous cell carcinoma (3); oral cancer (3); osteoarthritis (3); systemic sclerosis (3); colorectal tumors (2); invasive lobular breast carcinoma (2); leukemia (2); prostate adenocarcinoma (2); rectal cancer (2); adenoma (1); albuminuria (1); amoebiasis (1); amyloid (1); anaplastic large cell lymphoma (1); anaplastic thyroid cancer (1); anemia (1); autoimmune disease (1); benign breast tumor (1); brain cancer (1); breast disease (1); cardiovascular disease (1); cervical adenocarcinoma (1); cervical intraepithelial neoplasia (1); chronic kidney disease (1); clear cell renal cell carcinoma (1); ductal carcinoma (1); dysplastic nevi (1).
A further 26 diseases each share a sentence with CTHRC1 in 1 paper.